MYL6B (myosin light chain 6B)
Description:
Regulatory light chain of myosin. Does not bind calcium.
Synonyms: MLC1sa
Tractability: Small molecule: a structure with a bound ligand is known. PROTAC: ubiquitination databases record sites on it; its protein half-life has been measured.
Gene: Protein-coding gene on chromosome 12 (56,151,966 to 56,159,647, forward strand). Ensembl gene ENSG00000196465.
Pathways (Reactome):
Muscle contraction: Smooth Muscle Contraction
Gene Ontology:
Molecular function: protein binding; cytoskeletal motor activity; microfilament motor activity; structural constituent of muscle; calcium ion binding
Biological process: muscle contraction; muscle filament sliding; skeletal muscle tissue development
Cellular component: extracellular exosome; cytosol; muscle myosin complex; myosin complex; myosin II complex; unconventional myosin complex
Genetic constraint (gnomAD): Loss-of-function variants: 19 observed, 25.74 expected, observed/expected ratio (o/e) 0.74, 90% interval 0.51 to 1.08. The upper end of that interval is the gene's LOEUF score, 1.08, which puts it in group 4 of 6, group 1 being the genes least tolerant of losing a copy. Missense variants: 230 observed, 277.77 expected, observed/expected ratio (o/e) 0.83, 90% interval 0.74 to 0.92. Synonymous variants: 90 observed, 103.62 expected, observed/expected ratio (o/e) 0.87, 90% interval 0.73 to 1.03.
Homologues: Orthologues: macaque MYL6B (98% identical), chimpanzee MYL6B (96% identical), guinea pig MYL6B (96% identical), rat Myl6bl1 (93% identical), mouse Myl6b (91% identical), dog MYL6B (90% identical), pig MYL6B (88% identical), rat Myl6bl1 (86% identical), zebrafish myl6 (52% identical), zebrafish zgc:153867 (52% identical), tropical clawed frog myl6 (48% identical), Drosophila melanogaster Mlc-c (37% identical), and 2 more. Paralogues in human: MYL4 (62% identical), MYL1 (62% identical), MYL3 (59% identical), MYL6 (58% identical).
Diseases named in the same sentence as MYL6B in open-access papers:
MYL6B is named in the same sentence as 19 diseases in open-access papers, as found by Europe PMC text mining. Sharing a sentence is not in itself a finding about the gene and the disease. The quoted sentences say what the papers report.
hepatocellular carcinoma (3 papers, 2018 to 2022). A malignant tumor that arises from hepatocytes. "RPS21 and MYL6B in RI were associated with poor prognosis of patients with ESCA; they have been validated as oncoproteins in prostate tumor and hepatocellular carcinoma, respectively." (PMID 36466711, 2022). "Recently, increasing attention has been paid to the role of MYL6B in the progression of various cancers, including colon cancer and hepatocellular carcinoma." (PMID 33817240, 2020). "We also investigated the role of MYL6B in hepatocellular carcinoma by clone formation assay and by determining the correlation between its expression and prognosis of HCC patients." (PMID 29439719, 2018). "As an essential light chain for nonmuscle Myosin II (NMII), MYL6B has key impacts on hepatocellular carcinoma by binding to MDM2." (PMID 33817240, 2020).
rectal adenocarcinoma (3 papers, 2020 to 2023). "The overexpression of MYL6B closely correlated with the worse survival of patients with rectal adenocarcinoma." (PMID 33817240, 2020). "Based on these analyses, the proliferation, migration, and invasion of rectal adenocarcinoma cells after MYL6B knockdown in vitro were evaluated." (PMID 33817240, 2020). "The data showed that overexpression of MYL6B was observed in rectal adenocarcinoma tissues and correlated with a poor prognosis of patients." (PMID 33817240, 2020). "Next, we examined the biological functions of MYL6B in rectal adenocarcinoma cells after MYL6B knockdown." (PMID 33817240, 2020). "This study illustrated the role of MYL6B in rectal adenocarcinoma, suggesting a potential therapeutic target for its progression and diagnosis." (PMID 33817240, 2020). "Profiles on the Oncomine dataset, GEPIA website, and UALCAN-TCGA database were searched to assess the MYL6B expression level in rectal adenocarcinoma tissues and normal tissues." (PMID 33817240, 2020). "These in vitro results aligned with the finding that upregulated MYL6B is accompanied by poor prognosis in patients with rectal adenocarcinoma." (PMID 33817240, 2020). "In summary, this study elaborated on the promoting effect of MYL6B in rectal adenocarcinoma progression, thus providing novel insight for strategies of clinical diagnosis and drug application in the future clinical study." (PMID 33817240, 2020). "This study was designed to explore the biological significance of myosin light chain 6B (MYL6B) in rectal adenocarcinoma." (PMID 33817240, 2020). "The data obtained from the Oncomine dataset, GEPIA website, and UALCAN-TCGA database showed that the MYL6B expression in rectal adenocarcinoma was higher than that in human normal tissues (P < 0.01)." (PMID 33817240, 2020). "Meanwhile, the EMT process was also hindered in rectal adenocarcinoma cells after transfection with si-MYL6B." (PMID 33817240, 2020). "In total, we observed that overexpression of MYL6B could result in poor prognosis in patients with rectal adenocarcinoma, and cell viability, invasion, and migration were suppressed because of MYL6B knockdown." (PMID 33817240, 2020). "Functional in vitro experiments revealed that MYL6B knockdown could inhibit proliferation, migration, and invasion of rectal adenocarcinoma cells, while promote cell apoptosis." (PMID 33817240, 2020). "Additionally, the MYL6B expression in rectal adenocarcinoma based on individual cancer stages, gender, age, histological subtypes, and nodal metastasis status also revealed statistical significance (Figure A1)." (PMID 33817240, 2020). "Given the inhibitory effect of MYL6B knockdown on invasion and migration in rectal adenocarcinoma cells, we hypothesized that this inhibition is regulated through the EMT pathway." (PMID 33817240, 2020). "Taken together, all the results determined that MYL6B is a putative driver gene in rectal adenocarcinoma, and extensive research should be performed in the future to detect a potential mechanism through in vivo experiments to verify the results obtained in this study." (PMID 33817240, 2020). "Moreover, the qRT-PCR analysis demonstrated that MYL6B was also upregulated in human rectal adenocarcinoma cell lines (HT-29, SW1116, HCT116, and SW480) at different degrees when compared with that of human normal cell line Hs680.Rec (P < 0.01)." (PMID 33817240, 2020). "Therefore, in the present study, the expression level and prognostic significance of MYL6B in rectal adenocarcinoma were analyzed." (PMID 33817240, 2020). "It revealed that MYL6B may be a new prognostic marker in rectal adenocarcinoma." (PMID 33817240, 2020). "In order to determine the role of MYL6B in rectal adenocarcinoma, the overall survival curve was constructed by the Kaplan–Meier method, indicating that upregulation of MYL6B in patients with rectal adenocarcinoma significantly correlated with poor prognosis (P = 0.022)." (PMID 33817240, 2020).
rectal adenocarcinoma (continued). "Considering the relative expression of MYL6B in different cell lines, we selected the HCT116 and SW1116 cell lines as experimental materials due to the higher MYL6B expression level in comparison to the remaining rectal adenocarcinoma cell lines HT-29 and SW480 (P < 0.01)." (PMID 33817240, 2020). "However, the function of MYL6B in rectal adenocarcinoma has not yet been determined." (PMID 33817240, 2020). "Although no studies have investigated MYL6B in breast cancer, MYL6B overexpression promotes EMT in rectal adenocarcinoma, and in other epithelial cancers, high MYL6B expression is reported as a predictor of poor survival." (PMID 37128318, 2023).
breast carcinoma (1 paper, 2023). "YWHAB, SFN, and MYL6B are upregulated in breast cancer patient's blood, showing biomarker potential." (PMID 37128318, 2023). "Overall, SFN, YWHAB, TXNDC12, MYL6B, and PRDX4 expressions are significantly associated with breast cancer patient survival." (PMID 37128318, 2023). "MYL6B is significantly upregulated in breast cancer patient blood and can be identified at the highest level of protein certainty in human plasma." (PMID 37128318, 2023). "MYL6B mRNA expression is higher in breast tumor tissue than in normal tissue, and in luminal A breast cancer, MYL6B expression shows a significant positive correlation with miRNA cluster expression." (PMID 37128318, 2023). "MYL6B expression is significantly upregulated in breast cancer patient blood at 3.42 log2 (TPM+1) compared to 3.06 log2 (TPM+1) in healthy participants’ blood samples." (PMID 37128318, 2023). "Therefore, identified upregulated secretory markers YWHAB, SFN, TXNDC12, and MYL6B show strong potential in establishing a battery of breast cancer biomarkers alongside pri-miR526b and pri-miR655." (PMID 37128318, 2023). "Thus, the potential of MYL6B as a blood-based breast cancer biomarker should be further explored." (PMID 37128318, 2023). "Thus, only MYL6B, YWHAB, and SFN expression in breast cancer blood reflected secretory protein expression." (PMID 37128318, 2023).
breast tumor (1 paper, 2023). "PSMB6 and MYL6B have the same expression in breast tumors and normal tissues." (PMID 37128318, 2023).
diabetes (1 paper, 2013). "In the diabetic sternohyoid, three of the five calcium channel genes with decreased expression (Fstl1, Atp2b3, Eef2k, Gpd2, Myl6b) were decreased in previous diabetes studies." (PMID 24199937, 2013). "The five increased calcium genes (Myl6b, Casq2, Itga7, Cacnb2 and Sln) have not had changed expression in previous diabetes studies." (PMID 24199937, 2013). "Myl6b has not been significantly changed in previous studies involving diabetes." (PMID 24199937, 2013).
leukemia (1 paper, 2018). A malignant (clonal) hematologic disorder, involving hematopoietic stem cells and characterized by the presence of primitive or atypical myeloid or lymphoid cells in the bone marrow and the blood. "Different research groups have already reported the overexpression of MYL6B in CD133+ hematopoietic stem cell in leukemia, in HBV related HCC, in HCC cell lines and correlated to the prognosis of leukemia patients." (PMID 29439719, 2018).
rotator cuff tears (1 paper, 2022). "For example, MYL6B has been proved that it can differentially expressed in patients with rotator cuff tears, while EGR1 is conducive to the repair of rotator cuff tears." (PMID 36111133, 2022).
tumor (4 papers, 2013 to 2023). "Based on the data obtained from the Oncomine dataset, GEPIA website, and UALCAN-TCGA database, this study confirmed the expression level of MYL6B in tumor specimens and cell lines." (PMID 33817240, 2020). "Firstly, we found that the mRNA level of MYL6B in HCC tumor tissues is dramatically higher than in normal liver tissues according to the RNA-seq data in the TCGA LIHC dataset." (PMID 29439719, 2018). "MYL6B is 5.74 log2 (TPM+1) in tumor tissue in contrast to 5.25 log2 (TPM+1) in normal tissue." (PMID 37128318, 2023). "Our study and all these previous reports suggest that MYL6B might have a crucial role in tumor." (PMID 29439719, 2018). "After systematic data curation, four upregulated (YWHAB, TXNDC12, MYL6B, SFN) and four downregulated (FN1, PSMB6, PRDX4, PEA15) markers in miRNA-overexpressed tumor secretomes were identified." (PMID 37128318, 2023). "Both miRNA-overexpression enhanced cell migration and invasion of tumor cells and cell migration and angiogenesis properties of HUVEC cells in the TME, so we speculate that MYL6B might be driving these phenotypes for miR526b and miR655." (PMID 37128318, 2023). "Moreover, we found that MYL6B protein is frequently overexpressed in 63.3% (19/30) of HCC tumor tissues compared to adjacent non-tumor tissues and normal livers by immunoblotting analysis." (PMID 29439719, 2018).
MYL6B also shares sentences with these, for which no sentence is quoted: cancer (3 papers); acute myeloid leukemia (1); adenocarcinoma (1); Adrenocortical Cancer (1); colon adenocarcinoma (1); embryonal carcinoma (1); infection (1); melanoma (1); mesothelioma (1); non-small cell lung carcinoma (1); prostate tumor (1).